RAD51D (RAD51 paralog D)
Diseases named in the same sentence as RAD51D in open-access papers (continued):
Sharing a sentence is not in itself a finding about the gene and the disease.
cancer (continued). "To identify cancer-specific promoters we first compared the expression levels of Rad51B, Rad51C, Rad51D and Rad52 in a panel of seven normal and seven cancerous cells lines." (PMID 24742710, 2014). "Here, we explored the utility of the HR gene Rad51B, Rad51C, Rad51D and Rad52 for transcriptionally targeted therapy of cancer." (PMID 24742710, 2014). "In order to identify alternative promoters with high specificity to cancer cells we examined the tumor specificity of Rad51 paralogs Rad51B, Rad51C, Rad51D and Rad52." (PMID 24742710, 2014). "Other homologous recombination DNA damage repair (HR-DDR) genes associated with other cancer risks besides breast and ovarian, such as ATM (n = 9), BARD1 (n = 4), BRIP1 (n = 2), CHEK2 (n = 5), PALB2 (n = 5), RAD51C (n = 1), and RAD51D (n = 7), accounted for an additional 4% (33/769)." (PMID 40065011, 2025). "PV were detected in 13 cancer predisposition genes including ATM (n=4), BLM (n=1), BRCA1 (n=1), BRCA2 (n=7), BRIP1 (n=1), CDKN2A (n=1), CHEK2 (n=9), FANCC (n=1), MUTYH (n=10), NBN (n=1), PALB2 (n=1), RAD51D (n=1) and STK11 (n=1)." (PMID 36091166, 2022). "Our targeted genotyping assays or review of available WES data revealed that none of the carriers identified in the cancer study groups also carried another one of our RAD51C or RAD51D candidate variants." (PMID 35565380, 2022). "Since RAD51D is frequently associated with epithelial carcinoma but not with non-epithelial sarcoma, this case provides novel evidence for the crucial role of the RAD51D splicing variant in risk elevation for malignancies, including non-epithelial tumors." (PMID 34838098, 2021). "This is the largest family-based study to date to estimate age-specific relative and absolute TOC and BC risks for RAD51C and RAD51D pathogenic variant carriers, confirming that RAD51C and RAD51D pathogenic variants are associated with TOC and BC risks, which vary by cancer-family history." (PMID 32107557, 2020). "A study found that in RAD51D carriers with two first-degree relatives affected with BC, lifetime risks increased to 40% while the risk was 20% for those with no significant cancer family history." (PMID 39202057, 2024). "To examine whether UCP1-CRISPRa mammary adipocytes might prevent cancer development in individuals at high lifetime risk of cancer, we co-cultured them alongside breast organoids from dissected patient-matched breast tissue of BRCA1/BRCA2/RAD51D mutation carriers." (PMID 39905264, 2025). "When delayed from age 45 years to 50 years, RRSO yielded fewer QALYs and cancers prevented despite slightly larger NMB for RAD51C, RAD51D, and BRIP1 PV carriers." (PMID 38334999, 2024). "Of the eight HRR genes examined, the median methylation observed at the promoter regions of RAD51D and XRCC3 was ≤25% in all samples across all cancer types assessed, suggesting absence of promoter methylation for these two genes." (PMID 39055334, 2024).
cancer (continued). "Our investigation clearly demonstrates that cancer cell lines, including an epithelial ovarian adenocarcinoma cell line characteristic of HGSC OC disease, complemented with the RAD51D p.Ser46Cys have impaired protein expression." (PMID 35565380, 2022). "Our results suggest that the RAD51C and RAD51D genes should be included in gene panel testing for TOC and BC to guide cancer surveillance and prevention." (PMID 32107557, 2020). "The five classical RAD51 paralogs [RAD51B, RAD51C, RAD51D, XRCC2 and XRCC3] are important components of the homologous recombination pathway that preserves genomic integrity and protects against cancer." (PMID 31584931, 2019). "Therefore, an RAD51C and RAD51D analysis should be implemented into the comprehensive multi-gene testing for high-risk OC patients, including early-onset OC patients without a family cancer history." (PMID 26057125, 2015). "Therefore, this study aims to describe the age of onset and clinicopathological characteristics of BC and OC patients with a PALB2, RAD51C, or RAD51D GPV and compare these characteristics to national cancer registry data." (PMID 40428378, 2025). "Loss of the integral HR pathway components in cancers with non-BRCA HR defects due to germline or somatic mutations in PALB2, RAD51B, RAD51C, or RAD51D, or their inactivation through promoter methylation, might be the cause of olaparib susceptibility." (PMID 35741017, 2022). "For comparison, no BRIP1, 2 RAD51C, and 2 RAD51D large mutations per ~ 11,000 subjects are reported in the gnomAD database, and 2 BRIP1, 5 RAD51C, and 3 RAD51D large mutations per ~ 10,000 cancer-free women older than age 70 are documented in the FLOSSIES database." (PMID 32359370, 2020). "The mutagenic processes result from loss of integral HR pathway components; therefore, cancers with non-BRCA HR defects, such as germline or somatic mutations in PALB2, RAD51B, RAD51C, or RAD51D, or their inactivation through promoter methylation, would also receive a positive treatment prediction." (PMID 31727117, 2019). "Biallelic loss of HRR genes, especially BRCA1, BRCA2, RAD51D, RAD51 C, and PPP2R2 A was linked to higher HRD scores in BRCA-associated cancers, while BARD1, RAD51D, RAD54L, BRCA1, and MRE11 were associated with elevated HRD scores in in other cancer types (non-BRCA cancers)." (PMID 40420266, 2025).
tumor (70 papers, 2009 to 2026). "In a phase II study on Rucaparib (ARIEL2), there were two RAD51D GPVs mutation carriers included in the trial, with both mutation carriers showing significant tumor responses to Rucaparib." (PMID 39202057, 2024). "The immunohistochemical analysis performed on tumor sections from patients carrying this specific germline RAD51D c.270_271dupTA; p.(Lys91Ilefs*13) mutation revealed low expression of RAD51D." (PMID 39202057, 2024). "Three tumours showed alterations in RAD51D, one of which showed a concomitant P/LP variant in BRCA2." (PMID 34680387, 2021). "The confirmatory genetic test performed after genetic counseling revealed that the RAD51D splicing variant detected in her tumor was of germline origin." (PMID 34838098, 2021). "Whereas BARD1, BLM, and RAD51D mutations have a possible ethnic association, we identified only partial support for tumor and family member associations due to the limited sample size." (PMID 32566746, 2020). "In addition, tumour 10 harboured a likely pathogenic germline RAD51D splice variant, c.738 + 1G > A, expected to contribute to BRCAness in this tumour since inactivation of this gene is known to result in HRD." (PMID 37316882, 2023). "The TCGA cohort contained four tumours with RAD51D mutations, corresponding to a frequency of 1.3%." (PMID 34680387, 2021). "We noted for non-BRCA1/BRCA2 tumours, only a small proportion displayed high HRDetect scores and were characterized by concomitant promoter hypermethylation or in one case a RAD51D splice variant previously reported as having unknown significance to potentially explain their BRCAness." (PMID 37316882, 2023). "Four out of six tumors with the frameshift variant RAD51D c.270_271dupTA; p.(Lys91Ilefs*13) were HRD-positive, indicating that the tumor cells with this variant have a high tendency to fail to repair DNA double-strand breaks by the HR DNA repair pathway." (PMID 39202057, 2024). "The IHC staining supported low expression of RAD51D in the initial tumor tissue, but the expression was restored after the correction of the open reading frame by the secondary mutation." (PMID 37833926, 2023). "Our in vitro assay reproduced the PARPi sensitivity of the inherited 2 bp duplication, and RAD51D and γ-H2AX foci formation assays confirmed that deficient HR repair existed in the first surgery tumor sample." (PMID 37833926, 2023). "Molecular signature analysis has previously been shown to be useful in the characterisation of variants, and the identification of high HRDetect and LOH in the tumour carrying the spliciogenic variant c.202G > A and LOH at the RAD51D locus illustrate this." (PMID 37316882, 2023). "Low IHC staining of RAD51D was observed in the tumor section derived from the first surgery, which resulted in the HR defect and it becoming sensitive to PARPi." (PMID 37833926, 2023). "The difference in RAD51D protein expression in tumor samples between the first surgery, second surgery, and liver biopsy demonstrated the roles of primary mutation and secondary mutation in RAD51D function." (PMID 37833926, 2023). "Upon review of the RAD51 paralogs, both RAD51B (7th percentile) and RAD51D (6th percentile) showed low RNA expression in the tumor compared to the TCGA STAD dataset." (PMID 36964191, 2023). "In our cohort, a comprehensive tumor profile including homologous recombination genes (i.e., ATM, PALB2, RAD50, RAD51, RAD51B, RAD51C, RAD51D...) was performed for 100 cases, finding pathogenic alterations in four tumor samples, as previously reported." (PMID 35406410, 2022).
tumor (continued). "The extent of LOH in chromosome 17q varied across tumours with high HRD scores, with many showing hemizygous loss across BRCA1, RAD51C and RAD51D." (PMID 35039523, 2022). "The last patient had a tumor with two variants (BRCA2 p.Leu1620Phe and RAD51D p.Asp110Asn) predicted to be deleterious, but we were unable to ascertain which one was responsible for the response to treatment." (PMID 34206535, 2021). "LOH or AST mutation was detected in at least one tumor with PALB2, ATM, RAD51D, BARD1, BRIP1, RAD51C, or NF1 germline mutation." (PMID 32566746, 2020). "They identified Rad51 and Rad51D as key targets of miR-103/miR-107 that enabled the effects of the miRs in enhancing chemosensitivity of tumour cells." (PMID 27886180, 2016). "To identify novel tumor-specific promoters, we examined expression levels of Rad51 paralogs, Rad51B, Rad51C, and Rad51D as well as Rad52 in a panel of normal and tumor cell lines." (PMID 24742710, 2014). "BRCA2 mutations occur in 5–10% of prostate cases, and RAD51C/RAD51D, BRIP1, or BARD1 defects may broaden eligibility across tumor types." (PMID 40864792, 2025). "Given the complexity of HRD biomarkers, key assay features include the selection of HRR genes (BRCA1, BRCA2, PALB2, RAD51C, RAD51D), definitions of genomic scars (LOH, TAI, LST), mutational signatures analyzed, use of comparator samples, and tumor-specific HRD score calculations." (PMID 40864792, 2025). "In previous studies we have also demonstrated complete or partial loss of wild-type alleles in tumour DNA from FC carriers of RAD51C c.705G>T; p.Lys235Asn, RAD51D c.620C>T; p.Ser207Leu and FANCI c.1813C>T; p.Leu605Phe also from the analyses of RRCancer biobank materials." (PMID 36969007, 2023). "RAD51 and γ-H2AX foci formation assays illustrated that deficient HR repair in the first surgery tumor samples was complemented by the primary RAD51D mutation but not with the secondary RAD51D mutation." (PMID 37833926, 2023). "The RAD51D variant c.202G > A, p.(Gly68Ser) in contrast displayed LOH in this tumour." (PMID 37316882, 2023). "The tumour (tumour 11) with a somatic BRCA1 missense VUS and RAD51D c.202G > A variant were not classified as BRCA1-Like supporting that this tumour is driven by RAD51D and not BRCA1." (PMID 37316882, 2023). "The last tumour (tumour 11) with a high HRDetect score contained both a somatic BRCA1 missense variant and a germline RAD51D variant of unknown significance." (PMID 37316882, 2023). "Although the mechanisms of aberrant RAD51C and RAD51D in conferring risk to OC is unknown, our LOH analyses of tumour DNA from carriers are consistent with independent studies that have demonstrated loss of the protein function in tumour cells." (PMID 35565380, 2022). "As recently reported, an NGS profiling including HR genes (BARD1, BRIP1, PALB2, RAD51C, and RAD51D) could improve the rate of tumor with HRD by 5–6%, identifying patients who may mostly benefit from PARPi therapy." (PMID 35406410, 2022). "Reversions have not only been detected in tumours with BRCAm but also in tumours with mutations in other HRR genes such as PALB2, RAD51C and RAD51D, which reinforces the notion that mutations outside of BRCA genes that impact HRR are valid selection biomarkers for PARPi therapy." (PMID 35008208, 2021). "The authors identified Rad51 and Rad51D as key targets of miR-103 in tumor cells." (PMID 33317198, 2020). "In addition, reversion mutations leading to regained function of HR-proteins (e.g., BRCA1, RAD51C and RAD51D) in tumor cells result in PARP resistance." (PMID 30441849, 2018). "Our results indicated that germline truncation and missense variants in several genes were under selection in the tumour, with ATM, BRCA1, BRCA2 and RAD51C determined as significant from both truncation and missense analyses and BAP1, BRIP1, FANCM, PALB2 and RAD51D from truncation analysis alone." (PMID 26689913, 2015).
tumor (continued). "BRCA1 methylated tumours are also sensitive to PARP inhibition, as are tumours with mutations in other genes that function in repair of double strand breaks (DSBs), including RAD51C, RAD51D, ATM and PALB2, where tumours are described as having a “BRCAness” phenotype." (PMID 34445211, 2021). "RAD51 paralogs, including RAD51B, RAD51C, RAD51D, XRCC2 and XRCC3, have emerged as essential tumour suppressors, forming two subcomplexes, BCDX2 and CX3." (PMID 39268578, 2024). "In germline BRCA1/BRCA2/RAD51C/RAD51D/BRIP1 PVs, 44.4% (24/54) had a positive FH compared to 11.3% (28/249) of sporadic tumours (p < 0.001)." (PMID 34503154, 2021). "Deleterious alterations in DDR genes associated with increased sensitivity to PARP inhibitors in other tumor types (e.g. BRCA1, BRCA2, PALB2, RAD51C and RAD51D) were infrequent (9.4%) in ATLAS." (PMID 34030643, 2021). "Five HR cofactors – the RAD51 paralogs RAD51B, RAD51C, RAD51D, XRCC2 and XRCC3 – recently emerged as crucial tumor suppressors." (PMID 32669601, 2020). "However, to date, there is a lack of comprehensive data describing other tumor characteristics such as histological subtype and tumor size and stage in PALB2, RAD51C, and RAD51D GPV carriers." (PMID 40428378, 2025). "In a study of patients with tumor CGP-identified mutations in moderate risk breast and ovarian CSGs (ATM, BRIP1, CHEK2, PALB2, RAD51C, and RAD51D), 24% of patients with germline variants would not have met criteria for germline testing." (PMID 37568048, 2023). "We also observed no LOH in some of the tumour DNA from OC carriers of our RAD51C c.705G>T; p.Lys235AsnAs and RAD51D c.620C>T; p.Ser207Leu, as the DNA was extracted post-chemotherapy treatment, suggesting the possibility of stromal cell contamination." (PMID 36969007, 2023). "This is exemplified by PARPi used to treat breast, prostate, pancreatic or ovarian cancers with defects in the HR pathway, controlled by the tumour suppressors including (but not exclusive to) BRCA1, BRCA2, PALB2, RAD51C and RAD51D." (PMID 35567571, 2022).
RAD51D also shares sentences with these, for which no sentence is quoted: metastatic prostate carcinoma (4 papers); colorectal cancer (3); hereditary breast ovarian cancer syndrome (3); hereditary cancer (3); breast and (2); Familial adenomatous polyposis (2); hereditary cancer-predisposing syndrome (2); cervical dysplasia (1); endometrioid carcinoma of the ovary (1); esophageal cancer (1); fallopian tube cancer (1); glioma (1); Hereditary breast cancer (1); hereditary colorectal cancer (1); infection (1); infiltrating ductal carcinoma (1); invasive carcinoma (1); Li-Fraumeni syndrome (1); lung adenocarcinoma (1); lung carcinoma (1); lymphedema (1); lymphoma (1); medulloblastoma (1); mesothelioma (1); myeloma (1); ovarian mucinous carcinoma (1); ovarian serous carcinoma (1); pancreatic adenocarcinoma (1); peritoneal carcinoma (1); peritoneal mesothelioma (1).
A further 4 diseases each share a sentence with RAD51D in 1 paper.